IL2 (interleukin 2)
Diseases named in the same sentence as IL2 in open-access papers (continued):
Sharing a sentence is not in itself a finding about the gene and the disease.
neuroblastoma (continued). "Neuroblastoma cell lines, transfected ex vivo with the LID vector, were able to express high levels of IL-2 and IL-12, even if cotransfected with other cytokine genes." (PMID 12771934, 2003). "Dinutuximab beta is licensed in Europe for first-line treatment in patients with high-risk neuroblastoma, a GD2-positive malignant pediatric cancer, with and without a combination of interleukin 2 (IL-2)." (PMID 33572900, 2021). "An IL-2 immunocytokine targeting disialoganglioside (GD2) co-administered with LAK cells in a murine model for neuroblastoma resulted in the absence of detectable liver metastases." (PMID 33803078, 2021). "This first-of-its-kind study of IL-15 in an established neuroblastoma PDX model provided compelling preclinical data that IL-15 should be evaluated in future clinical studies, at least to compare its tolerability against that of IL-2 in paediatric patients." (PMID 33808071, 2021). "Lymphokine activated killers (which includes NK cells) from patients receiving IL-2 infusion, in combination with mouse or chimeric anti-GD2 antibody therapy, increased ADCC against neuroblastoma target cells, providing rationale for administering IL-2 in vivo to boost antitumor response." (PMID 34199783, 2021). "To further address the challenges of using modified MSCs to treat tumors, we generated a human adipose tissue-derived MSCs line (hADSCs) stably expressing IL2, to determine the effects of MSC-mediated IL2 delivery on SH-SY5Y neuroblastoma cell growth and immune modulation in vitro." (PMID 32560387, 2020). "The cytokines IFN-γ, IL-2, IL-7, IL-12, IL-15, IL-18, IL-21, and IL-27, promoted neuroblastoma regression via enhancing the efficacy of effector cells, whereas VEGF, IL-6, and IL-10 induced neuroblastoma progression through their immunosuppressive activities." (PMID 33322408, 2020). "In children with large refractory sarcoma or neuroblastoma, several phase I and II trials utilizing IL-2 as monotherapy have shown no measurable anti-tumor effects, and relapses occurred despite immune activation." (PMID 31847387, 2019). "By analysing a non-hematopoietic derived tumor, neuroblastoma, we focused on gene expression of WASp and IL-2 by tumor-infiltrating hematopoietic cells." (PMID 27477778, 2016). "Similarly, enhanced influx of IL-2 activated NK and CD8+ T-cells into neuroblastoma tumors increased survival in a neuroblastoma mouse model." (PMID 26452036, 2015). "Stimulation of neuroblastoma cells with the IL2/IL15 cytokine mix alone did not induce MHC I upregulation." (PMID 26452036, 2015). "Co-transfection of IL-2 and IL-12 in Neuro2a cells down regulated in vivo tumorigenicity and provided CD4+ T cell and CD8+ T cell mediated immunotherapeutic responses in syngenic neuroblastoma model." (PMID 21876694, 2012). "Indeed, tumour-targeted IL-2 has been shown to be capable of amplifying CD8+ T cells after IL-12 vaccination and enhancing MHC I-mediated killing in a murine model of neuroblastoma metastasis." (PMID 12771934, 2003). "The rationale for integrating GM-CSF and IL-2 with dinutuximab is to enhance antibody-dependent cellular cytotoxicity (ADCC), primarily by amplifying granulocyte and NK cell counts and activation, which constitute the primary mechanism of dinutuximab-induced anti-neuroblastoma immune reactions." (PMID 38927907, 2024). "In addition, in vivo studies of a subcutaneous xenograft model of neuroblastoma in nude mice showed that 7×2b CAR-T cells effectively cleared tumors in mice, and also secreted a large number of human IFN-γ, IL-2, and GZMS-B, suggesting 7×2b CAR-T cells have a powerful anti-tumor effect." (PMID 34778046, 2021). "Two phase I clinical trials (NCT00062855 and NCT01713439) studied the safety and dosage of an injection of neuroblastoma cancer cells that were genetically engineered to express XCL1 and IL-2, with the first using autologous cancer cells and the second using the allogenic SJNB-JF-IL2/Lptn cell line." (PMID 32075343, 2020).
neuroblastoma (continued). "Given the absence of a beneficial effect by adding sc-IL-2 to an 8 h infusion of dinutuximab beta, the standard treatment recommended by SIOPEN is dinutuximab beta with isotretinoin for maintenance therapy of high-risk neuroblastoma." (PMID 32013055, 2020). "To explore the hypothesis that zoledronic acid, IL-2 and anti-GD2 antibodies will synergize in a therapeutic combination, we evaluated in vitro cytotoxicity and tumor growth inhibition in the GD2 expressing cancers neuroblastoma and Ewing's sarcoma." (PMID 26942051, 2016). "While in vitro these NK cells proliferated and were able to produce cytokines upon IL-2 stimulation, in vivo the intratumoral NK cells were presumably inactive evidenced by the absence of MHC I expression in immunohistochemical stainings of neuroblastoma tumor sections." (PMID 26452036, 2015). "Tumor infiltration and signaling pathway for immune modulating cytokine IL-2 had a strong negative correlation with KIT expression, which is in line with our conclusion that KIT expression in neuroblastomas is not driven by immune infiltration." (PMID 35887076, 2022). "Anyhow, in the present study we could show a superior cytotoxicity of ex vivo IL-2 stimulated compared to unstimulated NK cells against the MHC-I negative cell line K562 and against a neuroblastoma (NB) cell line as well." (PMID 22096557, 2011).
leukemia (113 papers, 2005 to 2026). A malignant (clonal) hematologic disorder, involving hematopoietic stem cells and characterized by the presence of primitive or atypical myeloid or lymphoid cells in the bone marrow and the blood. "In agreement, transcriptome data integration together with GO enrichment analysis highlighted the enrichment for the IL-2/STAT5 signaling hallmark gene set in Myc + IL7Rmut derived leukemias, as well as for protein phosphorylation." (PMID 35581375, 2022). "Expression of interleukin-2 (IL-2) gene, encoding a key cytokine involved in leukemia cell survival, was evaluated by RT-PCR." (PMID 33110919, 2020). "Finally, we tested IL2-Smurf2 and its variants in an in vivo mouse model of leukemia and demonstrated its potential as a drug for the targeted treatment of cancer cells." (PMID 36612252, 2022). "In support, the administration of IL-2 in patients with relapsed or refractory leukemia and metastatic solid tumors leads to an increase in NK cell numbers and cytotoxic activity." (PMID 38698855, 2024). "Enriched programs included many of those that were found in the bulk leukemia, including inflammatory pathways such as interferon-γ and IL-2/STAT5 signaling, as well as an upregulation of KRAS signaling pathway-related genes." (PMID 38647535, 2024). "WT and MCJ KO CD8 CAR-T cells were generated, and after three expansions with IL-2 they were transferred to mice with E2a leukemia cells." (PMID 38789421, 2024). "WT and MCJ KO CD8 CAR-T cells were expanded with IL-2 for three expansions, extensively washed and incubated in medium alone for 24 h prior to setting the co-cultures with E2a leukemia cells for a killing assay." (PMID 38789421, 2024). "Curcumin reduced inflammation by inhibiting T cell-mediated Ca2+ mobilization and NFAT-regulated IL-2 and NF-κB production in freshly separated T cells and the Jurkat T leukemia cell line." (PMID 39770516, 2024). "A phase III trial of 320 AML patients in remission showed that treatment with histamine dihydrochloride and interleukin-2 (HDC/IL-2) significantly improved leukemia-free survival (LFS) versus standard of care in patients below 60 years of age." (PMID 37597015, 2023). "The association of cG250 with interleukin-2 (IL2) in preclinical studies induced relevant antibody-mediated cytotoxicity (ADCC) in RCC and leukemia." (PMID 35326544, 2022). "In vivo stimulation, that is, the activation of autologous γδ T cells using N-BPs + IL-2, induced few measurable responses in patients with leukemia." (PMID 34630403, 2021). "Phosphorylation of Tyr348 in GART was also reported in a human leukemia-derived T-cell line following stimulation with IL-2 or IL-15." (PMID 34283052, 2021). "On the one hand, IL-2 supports leukemia-directed lymphocytes, on the other, IL-2 simultaneously favors Treg cells driving the immune-suppressive leukemic microenvironment." (PMID 33804676, 2021). "Such IL-2-dependent leukemic cells are assumed to be in an initiation stage of leukemia/cancer development." (PMID 32210945, 2020). "Specifically, IFN-α, a representative FDA-approved cytokine has been used in the clinic to treat leukemia since 1986, and subsequently, recombinant interleukin-2 (IL-2) has been developed for cancer immunotherapy since 1992 59-61." (PMID 31695807, 2019). "Regarding leukemia, low-dose IL-2 administered to 84 patients with AML resulted in a pronounced increase of Tregs in the peripheral blood." (PMID 31195686, 2019). "In contrast, thymic naïve γδ T cells secrete IFN-γ in the presence of IL-2 or IL-15, through the de novo expression of T-bet and eomesodermin, and the release of cytotoxic molecules against leukemia cells." (PMID 28713381, 2017). "In agreement with this notion, delivery of IL-2 complexed to anti-IL-2 monoclonal antibody breaks established CD8+ T-cell tolerance in an FBL model of murine leukemia." (PMID 29250063, 2017).
leukemia (continued). "Accordingly, administration of DNR but not ARA-C promoted a significant increase of IFN-γ (p < 0.05), IL-1β (p < 0.01), IL-2 (p < 0.001), and IL-12 (p < 0.05) in the serum of leukemia-bearing mice." (PMID 29312358, 2017). "This view gains support from previous studies in which Tregs were targeted during immunostimulation with IL-2 in experimental leukemia using the combination of anti-CD25, aiming to deplete Tregs, and IL-2." (PMID 28721449, 2017). "A phase III clinical trial using histamine dihydrochloride in addition to IL-2 improved the leukemia-free survival of AML patients." (PMID 28210257, 2017). "While the RNA-T CD19 CART cells were superior to the OKT3/IL-2 T cells in controlling leukemia, they were slightly inferior to the Dynabead CAR T cells." (PMID 28523432, 2017). "NKCA induction by the AML leukemia cells target a subpopulation of peripheral blood NK cells and is interleukin-2 independent but is abrogated by a long-term culture of NK (LTNK) cells at 37°C." (PMID 26655503, 2016). "Having established that 3 doses of CD19-ENG T cells in conjunction with a single dose of IL2 can safely eradicate leukemia, we determined the minimal effective dose of CD19-ENG T cells without IL2." (PMID 27255991, 2016). "Immunotherapy with histamine dihydrochloride and low-dose interleukin-2 (HDC/IL-2) aims at boosting anti-leukemic functions of natural killer (NK) cells to reduce or eradicate residual leukemia." (PMID 26544512, 2015). "We assessed the relationship between receptor expression levels and responses to each of the cytokines (IL-3, GM-CSF, IL-2, IL-4, M-CSF, G-CSF and IL-6) in leukemia cells from 11 patients with AML." (PMID 26375984, 2015). "To search for these molecules we aligned IL-2 regulated genes detected by Affymetrix gene expression microarrays with the STAT5 cistrome identified by chip-on-ChIP analysis in an IL-2-dependent human leukemia cell line, Kit225." (PMID 23451206, 2013). "The present work sought to identify key cell survival and tumor relevant STAT5 target genes in IL-2 dependent human leukemia cells using gene expression and promoter microarray studies." (PMID 23451206, 2013). "Chicken IL-2 can modulate T-cell proliferation and cytotoxicity in vitro and in vivo and dysregulation of IL-2 expression is observed in diseases such as leukaemia." (PMID 20441582, 2010). "Leukemia patients who went into complete remission following chemotherapy developed a different type of leukemia after being placed on IL-2 therapy." (PMID 16478542, 2006). "These efforts finally yielded success following the discovery of IL-2 and its use to culture adult T cell lymphoma/leukemia cells." (PMID 15743526, 2005). "A chimeric protein, IL2-Smurf2, induced cell death in a mouse model of leukemia and lymphocyte." (PMID 40978141, 2025). "In another study using Jurkat T leukemia cells thymol treatment also reduced IL-2 production." (PMID 41169359, 2025). "In this study, we aimed to assess the role of IL-2 supplementation in the modulation of NK activating receptors and its effect on the antitumor activity against leukemia cells, including a xenograft mouse model of leukemia clearance." (PMID 38698855, 2024). "In addition, MSCs interfered with the secretory potential of leukemia-associated WT1- and ROR1-targeting CTL clones, inhibiting the release of IFNγ, tumor necrosis factor alpha, and IL-2." (PMID 38231344, 2024). "Our data showed that the expressed PD-L1–EGFP proteins were mainly localized on the cell membrane and could functionally inhibit interleukin-2 (IL-2) production by coculture with human leukemia cells, Jurkat T cells." (PMID 37027467, 2023). "This is based on the results of a Swedish study of 320 patients with AML in CR randomized to IL-2/HDC or observation which improved leukemia-free survival (LFS), especially in those in CR1 where 3-year LFS was 40% in the IL-2/HDC arm and 26% in the observation arm." (PMID 33604298, 2020).
leukemia (continued). "Because of the decrease of leukocytes in GALT in leukemia, we investigated whether interleukin-2 (IL-2) expression levels changed as well." (PMID 30934014, 2019). "Our results showed that the GALT structure is severely altered in leukemia, at least in part due to the suppression of the IL-2 gene expression in IEL, which may also effect cytokine production in LP." (PMID 30934014, 2019). "Finally, we found that exposure of human leukemia cells to PM III not only caused cytotoxicity, but also mediated an intrinsic immune reaction via enhanced Interferon, Il-2, Il-6, and Il-10 signaling." (PMID 30486233, 2018). "In our previous report comparing CD3/CD28 Dynabead T cells with OKT3/IL-2 T cells in the Nalm6 leukemia mouse model, the mice were treated with CD19 CAR RNA-electroporated T cells, and we found that OKT3/IL-2 T cells were inferior to the CD3/CD28 Dynabead T cells in controlling leukemia." (PMID 28523432, 2017). "Both peptides 9R and 9S1R kill both interleukin 2-dependent leukemia MOLT-4 (, Suppl." (PMID 28793867, 2017). "We hypothesized that human CIML NK cells, based on their enhanced persistence and function against leukemia, will safely provide improved results following adoptive transfer, compared to IL-2-activated or naïve NK cells." (PMID 25054077, 2014). "In addition, other pathways with high enrichment consisted of interleukin-2 signalling, which has been reported to be a key signalling pathway required for the survival of leukaemia initiating cells in chronic myeloid leukaemia; moreover, this has been shown to be an early change." (PMID 40495353, 2025). "Collectively, these results imply that IL-2 deprivation may dampen the outcomes of NK cell therapy for leukemia patients with a significant effect on NKp30 expression and function, which could be circumvented by the overexpression of a stimulatory NKp30 isoform." (PMID 38698855, 2024). "Both IFNG and IL2 mRNA were increased in the peripheral blood mononuclear cells (PBMCs) of GvHD patients that received a donor lymphocyte infusion for the treatment of relapsed leukemia after allogeneic HSCT and IL2 mRNA expression correlated with the progression of GvHD." (PMID 28421078, 2017). "However, phase III trial results showed that the combination of HDC and low-dose IL-2 improves the leukemia-free survival (LFS) of AML patients in complete remission (CR) after chemotherapy, thus supporting the clinical relevance of NOX2-mediated immunosuppression in AML." (PMID 28721449, 2017). "Thus, the Reinherz group chose to use their clone-specific MoAbs reactive with their REX T-leukemia cell line because they could grow the requisite number of cells more easily than their IL-2-dependent T cell clones." (PMID 23230441, 2012). "Again, this is in line with results describing higher leukemia-free survival and OS in −21M patients than in −21T AML patients during IL-2–based immunotherapy." (PMID 39857739, 2025). "IL-10's role as an anti-inflammatory cytokine involves inhibiting Th1 cytokines like IL-2 and IFN-γ, deactivating monocyte/macrophage proinflammatory cytokine synthesis, and playing a critical role in immune evasion in leukemia." (PMID 39118076, 2024). "Unlike control T cells, aPDL1-CART cells significantly halted the expansion and reduced the viability of co-cultured leukemia cells (Raji, CD46, and K562) overexpressing PD-L1, and this effect was paralleled by increased secretion of IL-2 and IFN-γ." (PMID 33653969, 2021). "Cells were maintained in low-dose IL-2 and re-inoculated into secondary MOLM-13 leukemia-bearing mice." (PMID 34750374, 2021). "In our previous work in a xenograft model of leukemia, we compared two T cell manufacturing methods that are commonly used in adoptive immunotherapy clinical trials, CD3/CD28 Dynabead and OKT3/IL-2." (PMID 28523432, 2017). "After stimulation by CD19 positive leukemia lines, the CD3/CD28 Dynabead T cells and OKT3/IL-2 T cells secreted similar amounts of IFN-gamma." (PMID 28523432, 2017).